RN7SL254P (RNA, 7SL, cytoplasmic 254, pseudogene)
Gene: Miscellaneous RNA gene on chromosome 4 (147,808,926 to 147,809,209, forward strand). Ensembl gene ENSG00000240014.
Homologues: Orthologues: chimpanzee Metazoa_SRP (98% identical), macaque Metazoa_SRP (94% identical), dog Metazoa_SRP (58% identical). Paralogues in human: RN7SL1 (81% identical), RN7SL2 (80% identical), RN7SL113P (79% identical), RN7SL3 (79% identical), RN7SL543P (79% identical), RN7SL45P (78% identical), RN7SL444P (78% identical), RN7SL44P (78% identical), RN7SL451P (78% identical), RN7SL679P (78% identical), RN7SL492P (77% identical), RN7SL220P (77% identical), and 702 more.